C11orf71 (chromosome 11 open reading frame 71)
Synonyms: FLJ20010; URLC7
Tractability: No criterion of Open Targets' tractability assessment is met for any kind of drug.
Gene: Protein-coding gene on chromosome 11 (114,391,443 to 114,400,511, reverse strand). Ensembl gene ENSG00000180425.
Subcellular location (Human Protein Atlas): Nucleoplasm; Nuclear bodies
Genetic constraint (gnomAD): Loss-of-function variants: 1 observed, 1.16 expected, observed/expected ratio (o/e) 0.86, 90% interval 0.24 to 1.88. That is too few expected variants to judge how well the gene tolerates losing a copy. Missense variants: 179 observed, 177.68 expected, observed/expected ratio (o/e) 1.01, 90% interval 0.89 to 1.14. Synonymous variants: 72 observed, 77.7 expected, observed/expected ratio (o/e) 0.93, 90% interval 0.76 to 1.13.
Homologues: Orthologues: macaque C14H11orf71 (93% identical), chimpanzee C11H11orf71 (92% identical), pig C11orf71 (69% identical), rabbit C11orf71 (68% identical), mouse Gm5617 (63% identical), rat C8h11orf71 (63% identical), dog C11orf71 (56% identical).
Diseases named in the same sentence as C11orf71 in open-access papers:
C11orf71 is named in the same sentence as 2 diseases in open-access papers, as found by Europe PMC text mining. Sharing a sentence is not in itself a finding about the gene and the disease.
C11orf71 shares sentences with these, for which no sentence is quoted: glioma (1 paper); oligospermia (1).